IL1B (interleukin 1 beta)
Diseases named in the same sentence as IL1B in open-access papers (continued):
Sharing a sentence is not in itself a finding about the gene and the disease.
Cognitive impairment (continued). "The MGCs, Mφs, and sera of the PARK2 mouse model displayed decreased expression of parkin and its link to the increased generation of pro-inflammatory cytokines and chemokines (e.g., IFNβ1, TNFα, IL-1β, IL-12, IL-13, IL-17, CCL2, and CXCL1), loss of DA neurons, and cognitive defects in PD." (PMID 34239490, 2021). "Importantly IL-6, IL-1β and IFNβ or IFN-dependent responses were exaggerated in older animals, both in plasma and in brain and this was associated with significantly worse cognitive impairments in aged animals." (PMID 33442686, 2021). "Finally, patients with PD and cognitive deficit (MMSE < 26) (n = 51) exhibited significantly increased plasma EV pro-IL-1β, IL-6, TNF-α, and IL-10 levels and a significantly decreased TGF-β1 level." (PMID 33803292, 2021). "In addition, increased inflammatory mediators, such as tumour necrosis factor alpha and interleukin-1 beta (IL-1β), are correlated with cognitive deficits for patients with late-stage Alzheimer’s disease." (PMID 32954291, 2020). "Therefore, inflammasome NLRP3, ASC, caspase-1, GSDM-D, IL-1β, and IL-18 are key signaling molecules for inflammation and cell pyroptosis and are involved in the process of CI and other cognitive disorders." (PMID 31781266, 2019). "Adiponectin, leptin, and IL-1β in elderly diabetic patients with mild cognitive impairment." (PMID 31969813, 2019). "High concentrations of IL1-β and TNF-α in the brain are associated with cognitive impairments." (PMID 28832497, 2017). "According to our data, Aβ and IL-1β may synergistically impair the retrograde trafficking pathway (via different mechanisms), thus, contributing to cognitive impairment in late AD stages." (PMID 28153028, 2017). "Based on our in vivo and in vitro results, we propose a CNS amplification loop between IL-1β and IL-33 produced by microglia and oligodendrocyte respectively, which may contribute to the early cognitive defects before ECM development." (PMID 28448579, 2017). "Although the precise mechanisms remain unclear, accumulating evidence suggests that neuroinflammation plays a central role in surgery-induced cognitive impairment, which was confirmed by the up-regulation of IL-1β in the hippocampus in the present study." (PMID 27790135, 2016). "During the past few years, an increasing amount of evidence has supported the view that the excessive release of proinflammatory cytokines, including tumor necrosis factor (TNF)-α, interleukin (IL)-1β and IL-6, is involved in cognitive impairment after surgery and anesthesia." (PMID 23613842, 2013). "We found that pretreatment with minocycline mitigated isoflurane-induced cognitive deficits and suppressed the isoflurane-induced excessive release of IL-1β and caspase-3 in the hippocampal CA1 region at 4 h after isoflurane exposure, as well as the number of TUNEL-positive nuclei." (PMID 23613842, 2013). "Deficits in the contextual fear conditioning paradigm have been clearly shown to rely on direct action of IL-1β on neurons of the hippocampus but it remains unclear how cognitive impairment occurs after systemic inflammation in most paradigms." (PMID 23840908, 2013). "With the use of lidocaine as a tool, our data also indicate that isoflurane-induced cognitive impairment may be mainly on the learning process under current experimental conditions and that this impairment may be mediated by IL-1β." (PMID 23251531, 2012). "One important and novel finding of our study is that IL-1β may play a critical role in isoflurane-induced cognitive impairment." (PMID 23251531, 2012). "In addition, decreases in the expression levels of ASC, Caspase-1, and IL-1β/IL-18 have been shown to alleviate the cognitive impairment of gerbils after I/R, and ASC exacerbates ischemic neurological deficits and inflammatory reactions in an NLRP3-dependent manner." (PMID 38441564, 2024).
Cognitive impairment (continued). "The levels of pyroptosis signaling pathway were significantly upregulated in cognitive impairment, together with the release of large amounts of inflammatory substances such as IL-1β and IL-18, resulting in a cascade of inflammatory reactions, which could be harmful to brain tissues." (PMID 37332874, 2023). "However, cognitive impairment was positively correlated to IL-1β at D1 (P=0.040)." (PMID 37878890, 2023). "Therefore, the hypercapnia resulting from lung-protective ventilatory strategies used in acute respiratory distress syndrome (ARDS) patients may lead to neuroinflammation and cognitive impairment via a microglial NLRP3/IL-1β-dependent mechanism." (PMID 37189617, 2023). "Elevated levels of IL-1β have also been detected in patients affected by memory deficits such as mild cognitive impairment and Alzheimer’s disease (AD), thus suggesting that IL-1β overproduction may be an early factor concurring to AD pathogenesis and progression." (PMID 37261502, 2023). "Additionally, the disturbance of the intestinal microbial flora has the potential to initiate the secretion of peripheral pro-inflammatory cytokines, namely IL-1β and IL-6, resulting in heightened permeability of the blood-brain barrier, disruption of the CNS, and subsequent cognitive impairment." (PMID 38108273, 2023). "In conclusion, the present results suggest that fisetin‐blocked NLRP3 inflammasome activation via promoting mitophagy in CMECs may suppress the secretion of IL‐1β into the CNS, reduce neuroinflammation, and contribute to the amelioration of cognitive impairment." (PMID 34837343, 2022). "Next, we investigated whether local IL-1β infusion was sufficient to induce cognitive impairment." (PMID 35982301, 2022). "Thus, the amplification loop between IL-1β and IL-33 in the CNS may contribute to plasmodium-induced cognitive deficits." (PMID 35974336, 2022). "Additionally, previous studies found that the abundance of pro-inflammatory Escherichia/Shigella in stool was higher in patients with cognitive impairment and brain amyloidosis than in the control group, and was positively related to the level of IL-1β, CXCL2 and NLRP3 inflammasome." (PMID 36405958, 2022). "In summary, our results highlight a mechanistic link between the expression of IL-1β/KCC2 and long-lasting cognitive impairment in a neonatal severe inflammation model and provide an underlying molecular target to prevent and/or treat cognitive disorders after early septic inflammation." (PMID 35883093, 2022). "Furthermore, it is demonstrated that SAE-induced cognitive impairment is dependent on IL-1β." (PMID 35111693, 2021). "Hence, autophagy-mediated microglial-mediated immunity focused on eliminating damage-associated molecular patterns, while preventing long-lasting neuroinflammation and neuronal damage, such as excessive IL-1β secretion, to improve postoperative cognitive impairment." (PMID 34079457, 2021). "Thus, IL-1β-producing microglia are required for IL-33 neurotoxic effects on cognitive impairment." (PMID 32917228, 2020). "NLRP3 or caspase-1 deficiency in APP/PS1 mice leads to reduced brain caspase-1 and IL-1β activation, increased microglial Aβ phagocytosis, reduced brain Aβ load, and protection of neuronal spine loss, long-term potentiation (LTP) decline, and cognitive deficits." (PMID 32391019, 2020). "Furthermore, preliminary experimental findings have suggested that NLRP3 inflammasome activation was linked to cognitive impairment after isoflurane anesthesia and isoflurane exposure induced the upregulation of NLRP3 and subsequently increased the level of IL-1β in the hippocampus of aged mice." (PMID 30873011, 2019). "In particular, if IL-1β is essential to proper learning and memory, and its levels are inhibited by both prenatal and adult alcohol exposure, this may increase the likelihood of cognitive deficits in the NOL task." (PMID 28973966, 2017).
Cognitive impairment (continued). "Notably, a previous study from our group has suggested that deficiency of CX3CR1 in the hTau mouse model of tauopathy resulted in accelerated tau pathology and cognitive impairment, which is mediated via IL-1β-p38 mitogen activated protein kinase (p38 MAPK) signaling pathway." (PMID 26089772, 2015). "Thus, we designed this study to determine whether proinflammatory cytokines, such as interleukin 1β (IL-1β), play an important role in isoflurane-induced cognitive impairment." (PMID 23251531, 2012). "Most recently, serum IL-1β has been found to be elevated in cases of mild cognitive impairment (MCI) that has a higher risk for conversion to dementia, possibly indicating that serum IL-1β may be useful for identifying those MCI patients at risk for converting to AD." (PMID 22454637, 2012). "Conversely, downregulation of microglial NLRP3 inhibited caspase-1 activation and pyroptosis, reduced release of IL-1β, improved AHN, and rescued cognitive deficits in DE mouse model." (PMID 41862685, 2026). "The central aim of our investigation was to assess cognitive impairment and to analyze the relationship between specific biomarkers - BDNF, BACE1, VEGF, GFAP and IL-1β and cognitive dysfunction in adults PWE." (PMID 40291844, 2025). "Changes in hippocampal neuroinflammatory markers were correlated with cognitive impairments (CA1: TNF-α, NF-κB1, IL-1β; DG: TNF-α, NF-κB1) and social deficits (CA1: TNF-α,IL-1β; DG: TNF-α, NF-κB1)." (PMID 40859005, 2025). "Furthermore, Akkermansia muciniphila increased SCFAs, reduced plasma endotoxins and TNF-α, IL-1β, and IL-6, and synergistically protectd blood-brain barrier integrity by upregulating the expression of intestinal Claudin-2/3 and cerebral Claudin-5, thereby improving post-stroke cognitive impairment." (PMID 40895486, 2025). "Canakinumab, an anti-IL-1β monoclonal antibody, completed a Phase II clinical trial (NCT04795466) to evaluate its efficacy and safety for cognition in participants with mild cognitive impairment or mild AD." (PMID 40427569, 2025). "In elderly patients with constipation, the relative abundance of Blautia reduced, while Blautia was positively correlated with mild cognitive impairment and negatively correlated with TNF-α, IL-6, and IL-1β, which was consistent with our results." (PMID 38398836, 2024). "Intraperitoneal injection of hemin induced cognitive impairment, increase of CD91 + cells, up-regulation of TNF-α and IL-1β, down-regulation of IL-6, activation of microglia, and activation of the TLR4/MyD88/NF-κB signaling pathway in rat brain." (PMID 38183122, 2024). "Strong stress induced by anesthesia and surgery accelerates nicotinamide adenine dinucleotide phosphate (NADPH) oxidase subtype NOX2 to induce microglia to release IL‐1β and downregulate BDNF, which is closely related to cognitive impairment." (PMID 38680509, 2023). "This leads to microglia activation and reduced Smad7–IkB pathway, which induces NF-κB nuclear translocation in neurons, increasing IL-1β which alters AMPA and NMDA receptors membrane expression, leading to cognitive impairment." (PMID 36593485, 2023). "In the current study, compared with the Control group, the hippocampal levels of IL-1β, IL-6, and TNF-α were increased in the MLPS group, which likely contributed to the cognitive impairment induced by maternal LPS exposure." (PMID 38074521, 2023). "The increased levels of IL-1β lead to enhanced activation of the IL-1 receptor which, in turn, alters membrane expression of AMPA and NMDA receptor subunits, leading to cognitive impairment." (PMID 36593485, 2023). "It is necessary to clarify the potential mechanism of Hsp22 in neuroinflammation-mediated cognitive impairment and the role of Hsp22 in regulating the activation of the NLRP3/Caspase-1/IL-1β pathway." (PMID 36934348, 2023). "As we discussed, pro-inflammatory cytokines (IL-1β, IL-6, and TNF-α) play a role in neuroinflammation and cognitive impairment." (PMID 37631080, 2023).
Cognitive impairment (continued). "Worsening cognitive impairment was correlated with a decrease in the cytokines IFN-γ, IL-1β, IL-2, IL-4, and IL-10." (PMID 37569491, 2023). "Increased serum IL-1β and TNF-α levels correlate with cognitive impairment and classical AD histopathologic brain lesions." (PMID 37760836, 2023). "In another study, treatment with ethyl pyruvate significantly reduced cognitive impairment in CLP mice by inhibiting NLRP3 and inducing IL-1β cleavage." (PMID 35958583, 2022). "We used traumatic surgical model and burns model in mice and found that peripheral inflammatory cytokines, including IL-6 and IL-1β, were main factor leading to the disruption of BBB and thus cognitive impairment." (PMID 36353359, 2022). "Compared with the dexmedetomidine group, IL-1β, TNF-α, and MDA levels in the hippocampus of the atipamezole and yohimbine groups increased, and cognitive impairment was aggravated." (PMID 35945306, 2022). "The M1‐type macrophage further releases the proinflammatory cytokines such as IL‐1β, TNF‐α, and IL‐6, thereby resulting in brain damage and cognitive impairment." (PMID 34951130, 2022). "Activated microglia secreted various neurotoxic and inflammatory factors, including IL-1β and TNF-α, ultimately leading to hippocampal neuroinflammation and hippocampus-dependent cognitive impairments." (PMID 35884806, 2022). "For instance, it has been reported that GMF contributes to cognitive deficits in mice, which may be associated with the stimulation of the MAPK and NF-κB signaling pathways, resulting in the up-regulation of pro-inflammatory cytokines such as TNF-α and IL-1β in astrocytes." (PMID 35974336, 2022). "The researches of IL-1β and CRP of cognitive impairment in psychiatric disorders is still controversial." (PMID 36406755, 2022). "In the current study, OVX induced cognitive impairment in mice and increased oxidative stress, serum CORT level, and expression of the inflammatory-related genes IL-1β, IL-6, and TNF-α in the frontal cortex and hippocampus." (PMID 35807554, 2022). "ROS cause rapid processing by NLRP3 inflammasomes and secretion of IL-1β, which is increased in the CNS of PWH with cognitive impairment." (PMID 35740279, 2022). "The presence of long-lasting increments in pro-inflammatory cytokines in the hippocampus, such as Il-6, IL-1β, and TNF-α, has led to the implication of neuroinflammation in brain aging and cognitive impairments." (PMID 35866081, 2022). "Conversely, TDF-AgNPs administration to diabetic rats improved cognitive deficits; and increased glutathione, SOD, and CAT, but reduced PFC malondialdehyde and IL-1β concentrations." (PMID 35122679, 2022). "In addition, peripheral IL-1β mRNA levels were found to be negatively correlated with verbal fluency and Broca’s area volume in patients with SCZ, and this study linked inflammatory blood biomarkers to cognitive deficits and reduced brain volume in SCZ patients." (PMID 36406755, 2022). "HMGB1/TLR4/IL-1β/IL-1R pathway, HMGB1/TNF-α/TRADD pathway, and TRAF-2 are the key initiators of neuroinflammation for epilepsy and cognitive impairments." (PMID 35656438, 2022). "Multivariate analysis showed that 95% CI of cytokines IL‐6, IL‐1β, TNF‐α, IFN‐α, and cognitive function was high, indicating a significant correlation between cognitive impairment and these cytokines." (PMID 34939360, 2022). "Here, VX-765 reversed cognitive deficits without altering increased pro-inflammatory Iba1+-microglia, Il-1β, TNF-α, and GFAP+-astrocytes, thereby seemingly excluding inflammation as a driver of cognitive impairment." (PMID 36220815, 2022). "Our results suggested that the cognitive impairment and hippocampal apoptosis of SAE rats depended on IL-1β." (PMID 35111693, 2021). "Activated microglia were found to participate in the secretion of pro-inflammatory cytokines, including IL-1β, IL-6, TNF-α, and TGF-β, thus aiding the development of cognitive impairment in individuals with neurological disorders." (PMID 35153660, 2021).
Cognitive impairment (continued). "Further, miR-485-3p ASO reduced the secretion of proinflammatory cytokines, including IL-1β and TNF-α, and eventually relieved cognitive impairment." (PMID 34884940, 2021). "In the present study, the repeated injection of LPS induced activation of NF-κB and expression of IL-1β and TNF-α and suppressed expression of BDNF and phosphorylation of CREB in mouse brain, resulting in cognitive impairment, as previously reported." (PMID 34579150, 2021). "Future studies should examine the roles of IL-1β and IL-18, two inflammasome-related cytokines, in CKD-induced cognitive impairment." (PMID 34572437, 2021). "Short-term (i.e., 10-24 weeks) moderate- to high-intensity strength training reduced LPS–IL-6, LPS, IL-1β, LPS–TNF-α and circulating concentrations of TNF-α and increased IL-10 in healthy elderly women and older people with cognitive impairment, respectively." (PMID 33936044, 2021). "For instance, IL-1β up-regulation potentiates neurodegeneration induced by dopaminergic signalling, whereas excessive secretion of TNF-α contributes to cognitive impairment." (PMID 33557113, 2021). "Many BafA1- or Rapa-induced up-regulated pro-inflammatory cytokines (e.g., IL-1B, TNFs, IL10, IL12, and IL13), correspond to the presence of CNS pathologies like cognitive impairment observed in patients with meningitis." (PMID 32225060, 2020). "Increased release of proinflammatory cytokines, including IL-1β and TNF-α, has been reported in the hippocampus of rodents after prolonged seizures, and contributes to cognitive impairment." (PMID 33161894, 2020). "Expression of IL1β and CCL2 is increased in AD, and both have been discussed as pathogenicity factors and biomarkers for, e.g., progression from mild cognitive impairment (MCI) to AD." (PMID 32878020, 2020). "Notably, restoration of this pathway by administration of MCC950 or Ac-YVAD-CMK could reduce NLRP3-mediated overactivation of neuronal pyroptosis, downregulate the expression of mature IL-1β and IL-18, rescue neuronal damage, and reduce cognitive impairments in SAE mice." (PMID 30276509, 2019). "Ischemia is known to increase the deleterious effect of Aβ production for synaptic impairment by induction of IL-1β and TNF-α of microglia, contributing to early cognitive impairment in Alzheimer's disease." (PMID 30911291, 2019). "In our present study, the degree of cognitive impairment following TZB therapy and the compensatory effects of ATV were confirmed using a passive avoidance test and measuring the levels of IL-6, IL-1β, and TNF-α." (PMID 30754707, 2019). "Melatonin and rapamycin significantly ameliorated the isoflurane-induced cognitive impairment and also led to a decrease in the melatonin levels as well as the expression levels of TNF-α, IL-1β, IL-6, and p-mTOR in the hippocampus." (PMID 31803045, 2019). "There were interaction effects on cognitive impairment, apoptosis of hippocampal neurons, activation of NLRP3 inflammasome, and upregulation of IL-1β between hypercapnia treatment and hypoxia treatment." (PMID 29304864, 2018). "There were also interaction effects on cognitive impairment, activation of NLRP3 inflammasome, and the upregulation of IL-1β between hypercapnia treatment and hypoxia treatment." (PMID 29304864, 2018). "Further studies conducted on the CNS have subsequently demonstrated that high levels of IL-1β, as occurring in neurological disorders such as multiple sclerosis and epilepsy, lead to an E/I imbalance, which might be responsible for – or contribute to – cognitive impairment." (PMID 29674955, 2018). "In response to inflammatory stimuli, including IL-33 through ST2 pathway, microglial cells released IL-1β which in turn activated oligodendrocytes to produce high levels of IL-33, documenting a CNS endogenous IL-33 inflammatory loop that may contribute to PbA induced cognitive disorders." (PMID 28448579, 2017). "Furthermore, IL-1β found at high levels in the hippocampus could be involved in cognitive deficits." (PMID 28448579, 2017).